HOXA13 (homeobox A13)
Diseases named in the same sentence as HOXA13 in open-access papers (continued):
Sharing a sentence is not in itself a finding about the gene and the disease.
hepatocellular carcinoma (16 papers, 2015 to 2024). A malignant tumor that arises from hepatocytes. "For instance, the high HOXA13 expression in hepatocellular carcinoma (HCC) is associated with patients’ clinical progression and predicts disease outcome." (PMID 34094932, 2021). "HOXA13 is over-expressed in primary hepatocellular carcinoma (HCC) and is strongly associated with hepatitis B and C virus infection." (PMID 31137568, 2019). "HOTTIP primarily coordinates expression of genes associated the HOXA locus in fibroblasts, and a recent paper showed a close association between HOTTIP and HOXA13 in hepatocellular carcinomas (HCCs)." (PMID 25912306, 2015). "Interestingly several studies investigating predicative biomarkers of cancer progression and patient outcomes in hepatocellular carcinoma have implicated the expression HOXA13 and HOTTIP as indicators of poor prognosis with high disease progression." (PMID 26633036, 2015). "(2018) declared that high expression of HOXA13 is correlated with poorly differentiated hepatocellular carcinomas and modulates sorafenib response in in vitro models." (PMID 31044561, 2019). "HOXA13, which is a flanking gene of rs6462008 and rs6462003 (the 1st and 4th most significant SNPs), is related to the control of cell proliferation, and its expression is increased in hepatocellular carcinoma and liver cirrhosis." (PMID 29975729, 2018). "Luca Quagliata and Ting-Ting Pan reported that abnormal HOXA13 expression was correlated with hepatocellular carcinoma (HCC) and that HOXA13 overexpression played an important role in HCC progression, metastasis, and poor prognosis." (PMID 26356815, 2015). "Notably, the lncRNAs HOTTIP, H19, HOTAIR, MALAT1, antisense Igf2r (AIR), HOXA13, GTL2 (also called MEG3) and uc002mb have been reported in association with hepatocellular carcinoma (HCC)." (PMID 26172293, 2015). "HOXA13, a HOX gene, is most overexpressed in HCC and is known to be directly regulated by the lncRNA HOTTIP, and high expression of HOXA13 correlates with poorly differentiated hepatocellular carcinomas and increases sorafenib response in vitro models." (PMID 39682093, 2024).
glioma (10 papers, 2015 to 2025). A benign or malignant brain and spinal cord tumor that arises from glial cells (astrocytes, oligodendrocytes, ependymal cells). "Compared to the Lenti-NC group, the Lenti-si HOXA13 treatment caused more apoptosis and increased the apoptotic rates in the four glioma cell lines." (PMID 26356815, 2015). "Our evidence suggested that HOXA13 was more than a simple transcription factor and implicated HOXA13 in glioma development and progression." (PMID 26356815, 2015). "We found that HOXA13 expression was associated with glioma grade and prognosis." (PMID 26356815, 2015). "Hoxa13 expression is upregulated in human gliomas and inhibits glioma cell apoptosis by activating Wnt and TGF-β-signaling pathway." (PMID 31165722, 2019). "Knowledges about beta-catenin regulation in glioma are recently increasing with R132H IDH1 mutation, FoxM1, TRIM33, HOXA13 as examples of positive or negative regulators." (PMID 27613837, 2016). "The down-regulation of HOXA13 in glioma cells resulted in a marked decrease in cell invasion in Transwell assays compared to the control cell type, and this effect was more significant in the U87 and U87-EGFRvIII cell lines." (PMID 26356815, 2015). "The expression of HOX10 and HOXA13 mRNA was increased in GBM specimens compared to lower-grade glioma." (PMID 26356815, 2015). "We also elucidated the involvement of the HOXA13 in glioma progression and uncovered the oncogene role of HOXA13; HOXA13 promotes GBM development by participating in the regulation of EMT due to the activation of a Wnt/beta-catenin and TGF-β signaling pathway." (PMID 26356815, 2015). "Here we detected the mRNA and protein expression of the 5′ HOXA genes and found the correlation between HOXA13 with tumor grade, poor prognosis in glioma." (PMID 26356815, 2015). "In order to explore the role of the 5′ HOXA genes in gliomas, we first measured the expression of HOXA9, HOXA10, HOXA11, and HOXA13 protein in 66 gliomas specimens of different grades." (PMID 26356815, 2015). "In the present study, we first analyzed the expression of HOXA9, HOXA10, HOXA11, and HOXA13 protein in glioma tissues; we then further analyzed the expression of HOXA9, HOXA10, HOXA11, HOXA13, and HOTTIP mRNA in the same samples." (PMID 26356815, 2015). "Our results demonstrated that HOXA13 induced glioma cell proliferation, cell cycle distribution, and cell invasion and inhibited apoptosis." (PMID 26356815, 2015). "Though data analysis generally showed a dysregulation of HOXA13 in different grade gliomas and a potential biological function of HOXA13 in glioma progression, the function of HOXA13 in GBM remained unclear." (PMID 26356815, 2015). "Altogether, these in vivo findings demonstrate that HOXA13 inhibits the proliferation of glioma cells in vivo." (PMID 26356815, 2015). "To study the biological implication of HOXA13 in glioma, we performed functional assays to determine HOXA13′s influence on glioma cell proliferation and invasion." (PMID 26356815, 2015). "As illustrated in, confocal microscopy showed HOXA13 staining to be attenuated in the nuclei of Lenti-si HOXA13 transfected glioma cells." (PMID 26356815, 2015). "Prior to implantation, we co-infected U87-EGFRvIII glioma cells with lentiviruses expressing luciferase and a Lenti-NC or Lenti-si HOXA13 for 48 h." (PMID 26356815, 2015). "The expression of HOXA13 was increased in high-grade gliomas compared to low-grade gliomas and NBT (P < 0.001)." (PMID 26356815, 2015). "A Pearson Correlation analysis was carried out using Matlab software and to identify target genes that were associated with HOXA13 in the CGGA, TCGA, and Rembrandt glioma samples." (PMID 26356815, 2015). "The down-regulation of HOXA13 triggered a reduction of nuclear β-catenin in four glioma cell lines, and p-β-catenin was induced by Lenti-HOXA13 in the cytoplasm." (PMID 26356815, 2015). "The expression of HOXA13 was also significantly up-regulated in lower-grade gliomas compared to NBT (p = 0.037)." (PMID 26356815, 2015).
glioma (continued). "Notably, WNT factors such as LEF1 and HOXA13 enhance cell migration and glioma development, particularly in high-grade gliomas 66,67." (PMID 40365286, 2025). "Besides, HOXA13 is a diagnostic marker for GBM and activated Wnt/TGF-β to promote glioma development." (PMID 29383189, 2017). "In four glioma cell lines, migration and invasion was inhibited by the introduction of a specific lentivirus containing a HOXA13 siRNA, and the β-catenin proteins levels in the nucleus were decreased after treatment with Lenti-si HOXA13." (PMID 26356815, 2015). "This was observed as significantly less fluorescence signal intensity in the nucleus compared to the Lenti-NC groups, suggesting that HOXA13 may contribute to an enhanced invasion ability of glioma cells dependent on TGF-β-induced EMT." (PMID 26356815, 2015). "We suggest that HOXA13 promotes glioma progression in part via Wnt- and TGF-β-induced EMT and is a potential diagnostic biomarker for glioblastoma and an independent prognostic factor in high-grade glioma." (PMID 26356815, 2015). "We therefore constructed a lentivirus containing a siRNA sequence targeting HOXA13 to verify whether HOXA13 plays a potentially functional role in glioma." (PMID 26356815, 2015). "The up-regulated pathways (focal adhesion, Wnt signaling, cell cycle, and TGF-β) suggested that high HOXA13 expression may contribute to the progression of glioma due to cell invasion, adhesion, and migration." (PMID 26356815, 2015). "In addition, the expression of HOXA10 and HOXA13 increased in the WHO IV gliomas compared to the WHO II & III gliomas, and the mRNA expression of HOTTIP increased from WHO II gliomas to WHO IV gliomas." (PMID 26356815, 2015). "This phenomenon suggests that the persistent activation of the TGF-β signaling pathway was due to a dysregulation of R-SMAD nucleocytoplasmic shuttling in gliomas and that HOXA13 may be involved in this process, especially in GBM." (PMID 26356815, 2015). "Overall, these differential pathways and functional analysis implied that HOXA13 may enhance glioma invasion and migration, and this process is carried out through several important cancer-related pathways." (PMID 26356815, 2015). "In the same way, HOXA13, belonging to the Homeobox (HOX) gene family, promotes glioma progression in part via Wnt- and TGF-β-induced EMT and, similar to LEF1, is a potential diagnostic biomarker for GBM and an independent prognostic factor in high-grade glioma." (PMID 29462960, 2018). "In addition, HOXA13 also inhibited glioma cell growth in glioma cell lines and a xenograft model." (PMID 26356815, 2015). "Thus, this evidences suggests that HOXA13 knockdown may cause G0/G1 arrest by inhibiting SMAD2/SMAD3 pathway and this process could be regulated by HOTTIP in glioma." (PMID 26356815, 2015). "Although HOXA13 is altered in a wide variety of human tumors, its role in glioma remains unclear." (PMID 26356815, 2015). "The expression of HOXA13 has been proposed as an activator of WNT and TGF-ß-induced epithelial to mesenchymal transition in glioma progression." (PMID 31073965, 2019). "By western-blot analysis, HOXA9, HOXA11, and HOXA13 were dramatically up-regulated in GBM, and HOXA10 merely showed a slight increase in high-grade glioma." (PMID 26356815, 2015). "However, there is not any previous study about the mechanisms of HOXA13 in cell cycle regulation in glioma cells." (PMID 26356815, 2015).
colorectal cancer (9 papers, 2020 to 2025). A primary or metastatic malignant neoplasm that affects the colon or rectum. "HOXA13 expression was up-regulated in in breast cancer, whereas it was down-regulated in colorectal cancer." (PMID 35349479, 2022). "Ectopic overexpression of ATP-citrate lyase and insulin-like growth factor 1 receptor rescues the decreased colorectal cancer metastasis induced by HOXA13 knockdown." (PMID 34722321, 2021). "In colorectal cancer, HOXA13 overexpression mediated by insulin-like growth factor 1 promotes metastasis through upregulating downstream targets ATP-citrate lyase and insulin-like growth factor 1 receptor." (PMID 34722321, 2021). "In colorectal cancer, HOXA13 was expressed more in normal colons than in malignant colons, and it was more highly expressed on the left side of the normal colon compared to the right side, indicating that differential HOXA gene expression occurs in an organized manner." (PMID 32296636, 2020). "HOXA13 expression increased in breast cancer, whereas it was downregulated in colorectal cancer." (PMID 32296636, 2020). "Here we show that expression of HOXA13 also increases in EAC and colorectal cancer, provides proliferative advantage to the cells and activates cancer-related gene transcription like Notch signaling." (PMID 34099670, 2021). "In colorectal cancer, IGF1 stimulation activates the IGF1R/AKT pathway and induces the transcriptional activation and expression of the transcription factor HOXA13, thereby promoting the in vitro migratory and invasive abilities of colorectal cancer cells and in vivo metastases formation." (PMID 38892104, 2024).
prostate carcinoma (8 papers, 2019 to 2023). A carcinoma that arises from epithelial cells of the prostate gland. "In the normal human prostate epithelium cell line RWPE-1, the HOXA13 gene and a prostate cancer GWAS identified a risk region form a repressive chromatin loop." (PMID 39872109, 2023). "The main role of HOTTIP and HOXA13 in prostate cancer has been underlined by the recent finding that PC risk elements are mainly related to HOXA13 and HOTTIP expressions, but not to other HOXA locus genes." (PMID 31137568, 2019). "Aberrant HOXA13 expression has been reported in prostate cancer (PC), where nuclear HOXA13 expression is strongly associated with histological grade and Gleason score." (PMID 31137568, 2019). "Together, this study demonstrated that HOXA13 is also a target gene transforming the roles of risk regulatory SNPs at the 7p15.2 locus that influences prostate cancer susceptibility." (PMID 31013831, 2019). "HOXA13 overexpression has been reported in bladder, brain, esophageal, gastric, liver, and prostate cancers." (PMID 37627895, 2023). "HOXA13, HOXA1, HOXA5, HOXA6, HOXA7, HOXA9, and HOXA10 are involved in prostate cancer, and they form a DNA loop with a locus that induces prostate cancer and regulates gene transcription." (PMID 37590265, 2023). "Homeobox A13 (HOXA13) gene which is upregulated almost 500-fold is reported to be an unfavorable prognostic factor and novel oncogene for prostate cancer 55 and is also suggested to be used as biomarker for prognosis in bladder cancer." (PMID 32550915, 2020).
bladder cancer (7 papers, 2019 to 2023). "Moreover, HOXA13 was an independent prognostic factor for the overall survival of bladder cancer patients, in which increased HOXA13 expression level was associated with a poorer bladder cancer prognosis." (PMID 37627900, 2023). "Regardless of either being employed alone or in combination with other genes, HOXA13 is a useful biomarker for stratifying bladder cancer patients into different groups of tumor stages and grades." (PMID 37627900, 2023). "Our study demonstrates that the HOXA13 protein is heterogeneously expressed in bladder cancer tissues with a predominantly nuclear localization." (PMID 37627895, 2023). "When bladder cancer cells progress to a more advanced stage, the HOXA13 protein is overexpressed and potentially plays a different role." (PMID 37627895, 2023). "The association between HOXA13/HOXB13 protein expression and demographic/clinicopathological characteristics of the bladder cancer patients was determined by chi-square analysis." (PMID 37627895, 2023). "Taken together, HOXA13 potentially plays different roles at the early and late stages of bladder cancer progression." (PMID 37627895, 2023). "In the urine samples of bladder cancer patients, the mRNA expression of a panel of genes (HOXA13, CDC2, IGFBP5, and MDK) was detected in 48% of stage Ta tumors, 90% of stage T1 tumors, and 100% of stage >T1 tumors at a specificity of 85%." (PMID 37627900, 2023). "Bladder cancer patients with high HOXA13 expression had shorter overall survival and disease-free survival as compared to those with low HOXA13 expression." (PMID 37627900, 2023). "Findings from our study suggest that HOXA13 is a putative oncogene in bladder cancer and that it has the potential to be developed into a clinically applicable biomarker for the detection of bladder cancer." (PMID 37627895, 2023). "The HOXA13 protein was predominantly localized in the nucleus of the bladder cancer cells, but in some tissues, it was also localized in both the nucleus and cytoplasm." (PMID 37627895, 2023). "Several studies have evaluated the utility of HOXA13 as a biomarker to detect bladder cancer using voided urine samples." (PMID 37627895, 2023). "Their findings were supported by other studies in which HOXA13 expression was elevated in low-stage tumors (pTa–pT1) of bladder cancer." (PMID 37627895, 2023). "HOXA13 was significantly higher expressed in bladder cancer tissues as compared to adjacent normal tissues." (PMID 37627900, 2023). "Hoxa13 and Hoxb13 are, for instance, known to have high expression in urinary bladder cancer Hox antisense intergenic RNA (HOTAIR) has been proposed as a marker in bladder cancer." (PMID 33402862, 2020). "High levels of HOXA13 homeoprotein have been found in bladder cancer tissues and positively correlated with lymph nodes metastases, TNM stage, pathological grade and patient survival." (PMID 31137568, 2019). "Hu, Chen, Cheng, Li, & Zhang (2017) suggested that dysregulated expression of homebox gene HOXA13 is related to the poor prognosis in bladder cancer." (PMID 31044561, 2019). "Although previous studies have shown the association of HOXA13 and HOXB13 with bladder cancer as well as the potential utility of HOXA13 as a biomarker for bladder cancer, findings from those studies are far from conclusive and require further robust validation." (PMID 37627895, 2023). "In addition, our study also aimed to determine the association of HOXA13/HOXB13 protein expression with various demographic and clinicopathological characteristics of bladder cancer patients." (PMID 37627895, 2023). "Therefore, HOXA13 helps to identify bladder cancer patient groups that require immediate surveillance and follow-up." (PMID 37627900, 2023). "Approximately 63.6% of the bladder cancer tissues harbored high HOXA13 expression." (PMID 37627895, 2023). "Our study suggests that HOXA13 may be involved in different stages of bladder cancer progression." (PMID 37627895, 2023).
bladder cancer (continued). "Hence, HOXA13 has huge potential as a biomarker for the diagnosis and prognosis of bladder cancer." (PMID 37627895, 2023). "The putative oncogenic and tumor suppressive roles of HOXA13 and HOXB13, respectively, suggest their potential utility as biomarkers in bladder cancer." (PMID 37627895, 2023). "The protein expression of HOXA13 and HOXB13 in formalin-fixed paraffin-embedded (FFPE) bladder cancer tissues was determined by immunohistochemistry (IHC) analysis." (PMID 37627895, 2023). "Future work will focus on validating the clinical significance of HOXA13 and HOXB13 as biomarkers for bladder cancer." (PMID 37627895, 2023). "The aim of our study was to profile and characterize the protein expression of homeobox A13 (HOXA13) and homeobox B13 (HOXB13) genes in Malaysian bladder cancer patients." (PMID 37627895, 2023). "This is crucial to thoroughly evaluating the potential of both HOXA13 and HOXB13 as biomarkers for bladder cancer." (PMID 37627895, 2023). "In this study, both HOXA13 and HOXB13 were selected after conducting a comprehensive review of the existing literature on the dysregulation of homeobox genes in bladder cancer." (PMID 37627895, 2023). "It quantifies four mRNAs which are overexpressed in bladder cancer: cycline-dependent kinase 1 (CDK1), homeobox A13 (HOXA13), midkine (MDK), and insulin-like growth factor-binding protein 5 (IGFBP5)." (PMID 30769831, 2019). "Therefore, our study aimed at profiling the protein expression of HOXA13 and HOXB13 in a cohort of formalin-fixed paraffin-embedded (FFPE) bladder cancer tissues from Malaysian bladder cancer patients." (PMID 37627895, 2023). "The majority of the FFPE bladder cancer tissues (94.5%, 104/110) positively expressed HOXA13, while only 5.5% (6/110) of these tissues were negative for HOXA13." (PMID 37627895, 2023). "Our study supports the oncogenic role of HOXA13 in bladder cancer, as this gene is involved in the early and later stages of bladder tumorigenesis, while HOXB13 may play a tumor suppressive role in bladder cancer." (PMID 37627895, 2023). "As such, the role of HOXA13 and HOXB13 in bladder cancer is not well studied." (PMID 37627895, 2023).